AURKA (aurora kinase A)
Diseases named in the same sentence as AURKA in open-access papers (continued):
Sharing a sentence is not in itself a finding about the gene and the disease.
hematological malignancies (12 papers, 2017 to 2025). "Several completed or ongoing phase I to III clinical trials investigating the effects of alisertib, a selective, small‐molecule AURKA inhibitor, in advanced solid tumors and hematologic malignancies have shown some promising results." (PMID 39789853, 2025). "As an AURKA inhibitor, alisertib has been used singly or combined treatment for advanced solid tumors and hematological malignancies in phase I, II, and III studies." (PMID 34337035, 2021). "In hematological malignancies, AURKA and AURKB overexpression are found in patients with cytogenetic abnormalities that are unfavorable to the prognosis and which compromise patients' survival." (PMID 33277547, 2020). "To date, clinical studies of AURKA inhibitors in hematologic malignancies have moved fast, but there has been slow progress in solid tumor studies." (PMID 30097580, 2018). "Aurora kinases (AURKA and AURKB) are mitotic kinases with an important role in the regulation of several mitotic events, and in hematological malignancies, AURKA and AURKB hyperexpression are found in patients with cytogenetic abnormalities presenting a unfavorable prognosis." (PMID 33277547, 2020). "AURKA and AURKB were downregulated upon curcumin treatment and both promote tumorigenesis in both solid and hematological malignancies." (PMID 34981672, 2022).
infection (6 papers, 2007 to 2024). The state of being infected such as from the introduction of a foreign agent such as serum, vaccine, antigenic substance or organism. "The infection efficiency of AURKA-shRNA lentiviruses was >80%." (PMID 39585848, 2024). "Especially, they found that the dynamic pattern of cell cycle genes such as CDK1, AURKA, and PLK1 are upregulated in early infection (4 hpi), and this upregulation tends to peak at 24 hpi and then precipitously decrease." (PMID 33060827, 2020). "In one recent study, productive HIV-1 cell-free infection of primary T cells was inhibited by a selective AURKA inhibitor but not by a selective AURKB inhibitor, barasertib." (PMID 37459363, 2023).
gastrointestinal tumors (4 papers, 2019 to 2025). "AURKA expression was higher in gastrointestinal tumors (e.g., READ and COAD) and lower in endocrine or nervous system tumors (e.g., THCA and LGG) at the RNA level." (PMID 40718709, 2025). "Inhibiting AURKA slows down the growth of gastrointestinal tumors by activating KRAS41." (PMID 34907282, 2021). "Firstly, various studies have indicated overexpression and amplification of AURKA in GI tumors 6-8." (PMID 31871591, 2019).
hematological cancers (4 papers, 2017 to 2021). "Overexpression of AURKA has been documented in solid tumors and hematological cancers." (PMID 28183295, 2017). "AURKA has emerged as a therapeutic target in various solid and hematologic cancers." (PMID 29291012, 2017).
breast (3 papers, 2014 to 2021). "MAP9 downregulation is associated with colorectal malignancy and could be used as a disease marker and a new drug target, while AURKA and PLK1 are upregulated." (PMID 24876664, 2014).
CNS tumor (1 paper, 2021). "AURKA gene rs8173 G > C exhibited a crucial function to CNS tumor susceptibility fall-off (GC/CC vs. GG: adjusted OR = 0.68, 95% CI = 0.46–0.998, P = 0.049)." (PMID 35201446, 2021). "In this research, AURKA gene rs8173 G > C polymorphism was identified to confer decreased CNS tumor susceptibility significantly in Chinese children." (PMID 35201446, 2021). "More potentially functional CNS tumor risk-associated SNPs in the AURKA gene and other genes should be investigated later." (PMID 35201446, 2021). "Continuous studies with a larger sample size are warranted to elucidate the effect of AURKA gene SNPs on CNS tumor risk." (PMID 35201446, 2021). "In this study, we have shed light on that AURKA rs8173 was associated with reduced CNS tumor risk." (PMID 35201446, 2021). "Besides, stratified analysis manifested carriers with AURKA gene rs8173 GC/CC were linked to decreased CNS tumor risk in the subgroup of male and clinical stages I + II diseases, with no findings in age and subtypes." (PMID 35201446, 2021). "Our research suggested that the AURKA gene rs8173 G > C could significantly reduce CNS tumor susceptibility in Chinese children." (PMID 35201446, 2021). "In this study, we assessed whether and to what extent AURKA gene single nucleotide polymorphisms (SNPs) (rs1047972 C > T, rs2273535 T > A, rs8173 G > C) were associated with CNS tumor susceptibility, based on a case–control analysis in 191 CNS tumor patients and 248 controls." (PMID 35201446, 2021). "Therefore, we are the first to speculate that the susceptibility of CNS tumors may be affected by AURKA gene SNPs." (PMID 35201446, 2021). "Therefore, we chose these AURKA SNPs to evaluate for the first time whether these AURKA genetic polymorphisms are associated with CNS tumor risk and the relationship’s strength in Chinese children." (PMID 35201446, 2021). "At the same time, there were no apparent correlations between other AURKA gene SNPs (rs1047972 and rs2273535) and CNS tumor susceptibility." (PMID 35201446, 2021). "Previous researches have shown that overexpression and amplification of the AURKA gene could induce multiple human malignancies, with which the connection of CNS tumor susceptibility has not been extensively studied." (PMID 35201446, 2021). "Given that AURKA SNPs are frequently observed in multiple human malignancies and the implication of AURKA SNPs in CNS tumors has not been investigated intensively." (PMID 35201446, 2021).
AURKA also shares sentences with these, for which no sentence is quoted: clear cell renal cell carcinoma (5 papers); Fanconi anemia (4); malaria (3); metastasis (3); pancreatic ductal adenocarcinoma (3); uterine serous carcinoma (3); acute lymphoblastic leukemia (2); basal cell carcinoma (2); bladder tumor (2); brain glioma (2); metastatic disease (2); neurodegenerative disease (2); non-Hodgkin lymphoma (2); papillary thyroid carcinoma (2); somnolence (2); T-cell acute lymphoblastic leukemia (2); T-cell non-Hodgkin lymphoma (2); acute GVHD (1); anaemia (1); Arthritis (1); AtaxiaTelangiectasia (1); atypical teratoid rhabdoid tumor (1); B-cell lymphomas (1); Barrett esophagus (1); benign breast tumors (1); benign prostatic hyperplasia (1); bone marrow fibrosis (1); carcinoma in situ of prostate (1); cervical squamous cell carcinoma (1); Chlamydia infection (1).
A further 58 diseases each share a sentence with AURKA in 1 paper.